TMEM81 (transmembrane protein 81)
Description:
Essential fertilization factor required for male fertility. Part of a conserved trimeric sperm complex with the essential fertilization factors IZUMO1 and SPACA6 which bridges sperm and oocyte membranes during fertilization by binding to IZUMO1R/JUNO on the oocyte.
Synonyms: UNQ2788; MGC75217; HC3107; KVLA2788
Tractability: Antibody: its Gene Ontology location is reachable by antibodies, with high confidence; UniProt places it where antibodies can reach, with medium confidence; UniProt predicts a signal peptide or a membrane-spanning region.
Gene: Protein-coding gene on chromosome 1 (205,083,129 to 205,084,460, reverse strand). Ensembl gene ENSG00000174529.
Subcellular location: Cell membrane
Subcellular location (Human Protein Atlas): Intermediate filaments
Gene Ontology:
Molecular function: protein-macromolecule adaptor activity
Biological process: sperm-egg recognition
Cellular component: plasma membrane
Genetic constraint (gnomAD): Missense variants: 251 observed, 281.92 expected, observed/expected ratio (o/e) 0.89, 90% interval 0.8 to 0.99. Synonymous variants: 113 observed, 111.65 expected, observed/expected ratio (o/e) 1.01, 90% interval 0.87 to 1.18.
Homologues: Orthologues: chimpanzee TMEM81 (99% identical), macaque TMEM81 (95% identical), pig TMEM81 (82% identical), dog TMEM81 (73% identical), rat Tmem81 (73% identical), mouse Tmem81 (72% identical), zebrafish tmem81 (26% identical).
Diseases named in the same sentence as TMEM81 in open-access papers:
TMEM81 is named in the same sentence as 4 diseases in open-access papers, as found by Europe PMC text mining. Sharing a sentence is not in itself a finding about the gene and the disease. The quoted sentences say what the papers report.
Infertility (1 paper, 2024). "Eight genes that result in male infertility (IZUMO1, SPACA6, TMEM95, TMEM81, SOF1, FIMP, DCST1, and DCST2) and an additional two that cause infertility in females (JUNO and CD9) have been identified." (PMID 38381819, 2024).
TMEM81 also shares sentences with these, for which no sentence is quoted: hepatocellular carcinoma (1 paper); male infertility (1); melanoma (1).